EWSR1 (EWS RNA binding protein 1)
Description:
Binds to ssRNA containing the consensus sequence 5'-AGGUAA-3'. Might normally function as a transcriptional repressor. EWS-fusion-proteins (EFPS) may play a role in the tumorigenic process. They may disturb gene expression by mimicking, or interfering with the normal function of CTD-POLII within the transcription initiation complex. They may also contribute to an aberrant activation of the fusion protein target genes.
Synonyms: EWS; EWS-FLI1
Tractability: Small molecule: a high-quality ligand is known. Antibody: UniProt places it where antibodies can reach, with high confidence; its Gene Ontology location is reachable by antibodies, with medium confidence. PROTAC: ubiquitination databases record sites on it; its protein half-life has been measured; a small molecule that binds it is known.
Gene: Protein-coding gene on chromosome 22 (29,268,009 to 29,300,530, forward strand). Ensembl gene ENSG00000182944.
Subcellular location: Nucleus; Cytoplasm; Cell membrane
Subcellular location (Human Protein Atlas): Nucleoplasm; Nucleoli
Gene Ontology:
Molecular function: identical protein binding; protein binding; RNA binding; transcription coregulator activity; nucleic acid binding
Biological process: regulation of DNA-templated transcription
Cellular component: nucleoplasm; nucleus; Cajal body; cytoplasm; plasma membrane
Genetic constraint (gnomAD): Loss-of-function variants: 14 observed, 88.04 expected, observed/expected ratio (o/e) 0.16, 90% interval 0.1 to 0.25. The upper end of that interval is the gene's LOEUF score, 0.25, which puts it in group 1 of 6, group 1 being the genes least tolerant of losing a copy. Missense variants: 633 observed, 883.76 expected, observed/expected ratio (o/e) 0.72, 90% interval 0.67 to 0.76. Synonymous variants: 302 observed, 297.08 expected, observed/expected ratio (o/e) 1.02, 90% interval 0.93 to 1.12.
Gene-disease validity (ClinGen):
ClinGen rates the evidence that EWSR1 causes each of these diseases.
amyotrophic lateral sclerosis (inheritance undetermined): Disputed. Amyotrophic lateral sclerosis (ALS) is a neurodegenerative disease characterized by progressive muscular paralysis reflecting degeneration of motor neurons in the primary motor cortex, corticospinal tracts, brainstem and spinal cord.
Cancer hallmarks: genome instability and mutations (suppresses)
Homologues: Orthologues: chimpanzee EWSR1 (99% identical), macaque EWSR1 (99% identical), dog EWSR1 (99% identical), pig EWSR1 (99% identical), rat Ewsr1 (99% identical), mouse Ewsr1 (98% identical), guinea pig EWSR1 (97% identical), tropical clawed frog ewsr1 (75% identical), zebrafish ewsr1a (60% identical), zebrafish ewsr1b (50% identical), Caenorhabditis elegans fust-1 (27% identical), Drosophila melanogaster caz (21% identical). Paralogues in human: FUS (45% identical), TAF15 (37% identical).
Diseases named in the same sentence as EWSR1 in open-access papers:
EWSR1 is named in the same sentence as 239 diseases in open-access papers, as found by Europe PMC text mining. Sharing a sentence is not in itself a finding about the gene and the disease. The quoted sentences say what the papers report.
Ewing sarcoma (699 papers, 1995 to 2026). A small round cell tumor that lacks morphologic, immunohistochemical, and electron microscopic evidence of neuroectodermal differentiation. "Treatment with the small molecule SP-2509 results in reversal of the transcriptional activity of the FET fusion that causes Ewing sarcoma, EWSR1::FLI1." (PMID 40852926, 2025). "FISH analysis on the aspirate using an EWSR1 break‐apart probe confirmed the presence of an EWSR1 fusion, a hallmark of Ewing sarcoma." (PMID 39907157, 2025). "At a genomic level, translocations involving EWSR1 are a hallmark of Ewing's sarcoma; this gene is responsible for making the EWS protein." (PMID 41267731, 2025). "Examples include MYCN amplifications driven by extrachromosomal DNA in NB and EWSR1::FLI1 fusions caused by chromoplexy in Ewing sarcoma." (PMID 41228232, 2025). "An EWSR1::FLI1 fusion was detected, a hallmark cytogenetic abnormality in Ewing sarcoma (EWS), seen in 85% of cases." (PMID 40630716, 2025). "Ewing sarcoma is an aggressive bone tumor of adolescence characterized by a hallmark EWSR1::ETS fusion oncogene." (PMID 41444391, 2025). "The majority of rare tumor subjects that exhibited a mutated EWSR1 gene had a specific diagnosis of Ewing sarcoma (other diagnoses included desmoplastic small round cell tumor and other rare tumors)." (PMID 38347552, 2024). "Ewing Sarcoma is an aggressive bone tumor primarily affecting children and young adults, frequently associated with EWSR1 gene fusions." (PMID 39682287, 2024). "Ewing sarcoma is an aggressive bone and soft-tissue cancer that is caused, in the majority of tumors, by an aberrant gene fusion between the EWSR1 and FLI1 genes." (PMID 39201282, 2024). "EWSR1−/− cells also show the accumulation of miRNA let-7g precursors, resulting in the downregulation of its mature form, a hallmark of Ewing sarcoma cells, underlining the role of EWSR1-mediated miRNA biogenesis in the context of oncogenesis." (PMID 39769457, 2024). "Ewing sarcoma is a cancer of children and young adults characterized by the critical translocation-associated fusion oncoprotein EWSR1::FLI1." (PMID 36793594, 2023). "Hematopoietic-associated fusions involving ERG also extend to EWSR1-ERG in 5-10% of Ewing’s sarcoma, and ELF4-ERG and FUS-ERG in acute myeloid leukemia." (PMID 37377909, 2023). "EWSR1 encodes EWS RNA binding protein 1, a transcriptional activator whose gene at 22q12.2 is also the first component of fusions found in the pediatric tumor Ewing sarcoma." (PMID 36604386, 2023). "Certain subtypes are strongly associated with genetic fusions, such as Ewing’s sarcoma (EWSR1::FLI1), alveolar rhabdomyosarcoma (PAX3/7::FOXO1), and synovial sarcoma (SS18::SSX1/2/4)." (PMID 36980578, 2023). "Instead, the epigenome of Ewing sarcoma (EWS) cells reflects the regulatory state of genes associated with the DNA binding activity of the fusion oncoproteins EWSR1::FLI1 or EWSR1::ERG." (PMID 38187702, 2023). "Using FISH analysis, the break-apart molecular probes (EWSR1 (22q12) Break – XL, Leica Biosystem, Nussloch, Germany) showed distinct broken red and green fluorochromes, diagnostic of Ewing sarcoma." (PMID 36129618, 2022). "In both Ewing sarcoma and certain leukemias, oncogenic gene rearrangements can fuse the 5′ end of EWSR1 to the 3′ end of transcription factor encoding genes." (PMID 34409300, 2021). "Of the top 50 protein targets that we identified, 15 were previously causally implicated in cancer, including EWSR1, the proposed driver of Ewing sarcoma development." (PMID 34662337, 2021). "Similar GO associations were enriched among genes affected by EWSR1 or EWS-FLI1 in Ewing sarcoma cells, suggesting the overlap in activity has a functional significance." (PMID 34035145, 2021).
Ewing sarcoma (continued). "MN1 alteration is one of the molecular hallmarks of the recently described HGNET-MN1 tumor subentity, while EWSR1 has long been known to be involved in Ewing sarcoma, even though the exact factors underlying its oncogenicity remain to be fully understood." (PMID 34417833, 2021). "Ewing's sarcoma is a family of tumors characterized by translocations generating the fusion between a gene encoding the EWSR1 and a gene encoding the ETS family of transcription factors." (PMID 34564939, 2021). "FUS/TLS, Ewing sarcoma (EWS: also known as Ewing sarcoma breakpoint region 1 (EWSR1)) and TATA-binding associated factor 15 (TAF15) belong to the FET family of DNA and RNA-binding proteins." (PMID 34069857, 2021). "Compared to results for Ewing sarcoma cells, the EWSR1 knockdown in HEK293T/17 cells caused levels of relatively few transcripts to significantly increase (n = 139) or decrease (n = 148) by >1.6-fold." (PMID 34035145, 2021). "Several IDPs associated with neurodegeneration are also oncogenes: EWSR1 (whose fusion with the transcription factor FLI1 causes Ewing's sarcoma) and FUS (whose fusion with the transcription factor CHOP causes myxoid liposarcoma)." (PMID 32364240, 2020). "This includes ALKF1174 and ALKR1275 mutations and MYCN amplifications in primary neuroblastomas, the BRAFV600E mutation in Langerhans cell histiocytosis, and EWSR1 translocations in Ewing sarcoma, to name a few." (PMID 31897843, 2020). "It is likely that many sites rely on fluorescence in situ hybridization (FISH) using the EWSR1 gene break-apart probe as the established molecular diagnostic test for Ewing sarcoma." (PMID 33488267, 2020). "Ewing sarcoma (EwS) is a rare, aggressive solid tumor of childhood, adolescence and young adulthood associated with pathognomonic EWSR1-ETS fusion oncoproteins altering transcriptional regulation." (PMID 32881892, 2020). "All four tumors manifested the diagnostic EWSR1 mutation and were treated with an Ewing sarcoma regimen." (PMID 29285586, 2018). "The pathogenesis of Ewing sarcoma is strongly linked to the presence of a translocation between the EWSR1 gene and a member of the ETS gene family." (PMID 27524931, 2016). "Genetic translocation of EWSR1 to ETS transcription factor coding region is considered as primary cause for Ewing sarcoma." (PMID 25751255, 2015). "Mutations in the EWSR-1 gene (Ewing sarcoma breakpoint region 1, 22q12.2) are known to cause ESFT as well as other mesenchymal tumors." (PMID 25614743, 2014). "Ewing sarcoma is characterised by translocations encoding fusion transcription factors with an EWSR1 transactivation domain fused to an ETS family DNA binding domain." (PMID 24667836, 2014). "Additionally, EWSR1 translocations, commonly associated with Ewing sarcoma and related tumors, were found in two recurrent CCOC cases." (PMID 41364259, 2025). "EWSR1 has been proven to be associated with the migration of anoikis cells in Ewing’s sarcoma." (PMID 40762284, 2025). "Similarly, Ewing’s sarcoma is another tumor associated with chromosomal rearrangements, distinguished by a genetic rearrangement of the EWSR1 gene on chromosome 22q12." (PMID 40697666, 2025). "EWSR1 rearrangement mutations are indicative of Ewing sarcoma, or peripheral PNET." (PMID 39170848, 2024). "Ewing’s sarcoma is the second most common bone malignancy in children or young adults and is caused by an oncogenic transcription factor by a chromosomal translocation between the EWSR1 gene and the ETS transcription factor family." (PMID 36194562, 2022). "Ewing sarcoma has been categorized as a ‘BRCAness’ tumor with emerging data characterizing a spectrum of DNA damage repair defects within individual Ewing tumors, including the presence of EWSR1::FLI1 itself, recurrent somatic mutations, and rare germline-based defects." (PMID 36483025, 2022).
Ewing sarcoma (continued). "EWSR1 is a polyfunctional protein that regulates cell function and aging by a variety of pathways, and is associated with the occurrence of mesenchymal tumors, multiple myeloma, Ewing’s sarcoma, and other tumors." (PMID 35686089, 2022). "Importantly, the levels of sincRNA are elevated in an Ewing sarcoma (EWS) cancer model system, where mutations in the EWS RNA-binding protein 1 (EWSR1) perturb the metabolism of nucleolar R-loops." (PMID 34287370, 2021). "Interestingly, this chromosomal region contains the EWSR1 gene, which causes Ewing sarcoma as well as neuroectodermal and other tumors." (PMID 33801093, 2021). "The greater need for ongoing surveillance for EWSR1-associated sarcomas lies with the more aggressive and malignant Ewing’s sarcoma (ES), desmoplastic small round cell tumour (DSRCT), clear cell sarcoma (CCS), myxoid liposarcoma (ML), and extra-skeletal myxoid chondrosarcoma (EMC)." (PMID 33669307, 2021). "Ewing's sarcoma family encompasses a group of highly aggressive, undifferentiated, intra- and extraosseous, mesenchymal tumors, caused by several types of translocations usually involving the EWSR1 gene." (PMID 27524931, 2016). "Ewing sarcoma is a prototypical chromosomal translocation-associated malignancy, in which virtually all cases harbor a balanced somatic translocation fusing the EWSR1 gene (EWS) to a member of the (E- twenty six) ETS-family of transcription factors, most commonly FLI1 (FLI)." (PMID 25093581, 2014). "Notably, our case excluded DICER1 mutations (associated with pediatric central nervous system tumors), EWSR1 rearrangements (a hallmark of Ewing sarcoma), and MDM2 amplification (common in liposarcoma and osteosarcoma), highlighting the molecular distinctiveness of HGMS." (PMID 40242239, 2025). "We analysed the spectrum of EWSR1-rearranged soft tissue neoplasms at our tertiary sarcoma centre, by assessing ancillary molecular diagnostic modalities identifying EWSR1-rearranged tumours and reviewing the results in light of our current knowledge of these and other Ewing sarcoma-like neoplasms." (PMID 28141799, 2017). "Here, the authors describe the establishment and characterization of four new, intrinsically immortal, patient‐derived Ewing sarcoma cell lines, including the first described cell line with an EWSR1::FLI1 type IV translocation." (PMID 41002248, 2026). "EWSR1::FLI1 is the only genetic alteration in an otherwise unaltered genome of Ewing sarcoma tumors." (PMID 42295992, 2026). "EWSR1 gene rearrangements were consistently observed in Ewing sarcoma and desmoplastic small round cell tumors." (PMID 41562936, 2026). "Surgical excision and histopathological examination confirmed Ewing sarcoma with EWSR1 gene rearrangement." (PMID 41625042, 2026). "Subtype-specific alterations were observed, including EWSR1 fusions in Ewing sarcoma and CDK4 and MDM2 amplifications in liposarcoma, reflecting well-established pathogenic mechanisms." (PMID 41562936, 2026). "This fine-tuning of such biological determinants has been termed the “Goldilocks principle” as related to expression levels of EWSR1::FLI1 in Ewing sarcoma, for example." (PMID 40299558, 2025). "The decrease in gene expression of EWSR1::FLI1-KDM6A targets identified by ChIP-seq was confirmed in a second Ewing sarcoma cell line, TC-71, upon KDM6A KO." (PMID 41085408, 2025). "Chromosomal translocations in Ewing sarcoma involve the EWS (EWSR1) gene at 22q12 and a gene from the ETS family of transcription factors." (PMID 40060231, 2025). "The involvement of EWSR1 gene accounts for 76 to 93% of chromoplectic events detected in Ewing Sarcomas." (PMID 40332527, 2025). "A number of Ewing sarcoma cell lines carrying the defining EWSR1::FLI1 fusion have already been established from both tumor and pleural effusion samples." (PMID 40134582, 2025). "Tumor transcriptome analysis identified an EWSR1::FLI1 fusion, with breakpoints distinct from those typically associated with Ewing's sarcoma." (PMID 40630716, 2025).
Ewing sarcoma (continued). "Ewing sarcoma is a small round-cell sarcoma characterized by gene fusion involving EWSR1 (or another TET family protein like FUS) and an ETS family transcription factor." (PMID 39158802, 2025). "Ewing sarcoma (ES) is a translocation-positive small round cell tumor characterized by chimeric fusions between the EWSR1 gene and ETS family members, most notably EWSR1-FLI1, which drives oncogenesis." (PMID 41141138, 2025). "For fusions, the EWSR1::FLI1 fusions were frequently and only found in bone and soft tissue sarcomas, specifically Ewing sarcomas, as their pathogenic hallmark." (PMID 41312385, 2025). "A large diversity offusion oncogenes was observed, primarily in one tumor, the three most commonbeing: EWSR1::Fli1 (n = 13) observed in Ewing sarcomas, PAX3::FOXO1 (n = 12) inrhabdomyosarcomas, and ETV6::RUNX1 (n = 8) in childhood leukemias." (PMID 40093400, 2025). "In Ewing sarcoma cell lines, a direct interaction between the EWSR1::FLI1 fusion protein and PARP1 was described." (PMID 40134582, 2025). "The Ewing sarcoma family of tumours is a group of malignant mesenchymal neoplasms characterized by characteristic EWSR1 gene rearrangement." (PMID 40666501, 2025). "Top-ranked SEs in Ewing sarcoma emphasized previously reported highly expressed or direct EWSR1::ETS targets such as BCL11B46,47, CAV148, CCND149, JAK150, NKX2-251,52, PRKCB53, or VRK18." (PMID 41444391, 2025). "In the EWING2008 trial, genomic EWSR1 fusion sequence spanning primers and probes were used for ctDNA quantification by digital droplet PCR in plasma samples from 102 patients with Ewing sarcoma." (PMID 40679665, 2025). "Ewing sarcoma is characterized by the presence of EWSR1 rearrangements with a member of the ETS family of genes." (PMID 40679665, 2025). "In ES (Ewing Sarcoma), hnRNPH1 regulates the splicing of the EWSR1::FLI1 fusion gene, promoting the production of oncogenic transcripts." (PMID 40507967, 2025). "Fluorescence in situ hybridization (FISH) confirmed EWSR1 gene rearrangement, establishing the diagnosis of Ewing’s sarcoma of the prostate." (PMID 41267731, 2025). "The FET (FUS, EWSR1, and TAF15) fusion oncogenes are characteristic for around 20 different sarcomas and leukemia, including FUS::DDIT3 in myxoid liposarcoma (MLS) and EWSR1::FLI1 in Ewing sarcoma (EWS), the two most common FET sarcoma entities." (PMID 40988026, 2025). "Translocations of FUS or EWSR1 can generate a large number of fusion proteins that drive several sarcomas, with the most notable being Ewing sarcoma." (PMID 40285687, 2025). "We have tested examples of Ewing sarcoma cell lines expressing EWS-FLI1, a fusion of the EWSR1 and FLI1 proteins, which is the driving mutation for 85% of Ewing sarcoma tumors." (PMID 40909543, 2025). "In Ewing sarcoma, small molecule YK-4-279 and its clinical derivative TK-216 have been labelled as first-in-class inhibitors of EWSR1::FLI1 and other EWSR1 fusions seen in Ewing sarcoma." (PMID 40983796, 2025). "Ewing sarcoma is a highly aggressive tumor arising in bones and soft tissues, driven by the fusion oncoprotein EWSR1::FLI1." (PMID 41085408, 2025). "The intersection obtained in A-673 was validated in a second Ewing sarcoma cell line, TC-71, in which we found 1,163 common peaks between EWSR1::FLI1 and KDM6A/KDM6B (P value < 0.05; FDR <10−5 in all cases)." (PMID 41085408, 2025). "Some sarcomas have specific molecular characteristics, such as SYT::SSX fusion in synovial sarcoma, EWSR1::FLI1 fusion in Ewing's sarcoma (ES), and MDM2 amplification in dedifferentiated liposarcoma (DDLS), leading to correct diagnosis and treatment." (PMID 40755265, 2025). "The first research paper on this topic, published in 1994, focused on identifying Ewing’s sarcoma, osteosarcoma, and other small round cell sarcomas through the detection of EWS/FLI-1 (EWSR1) fusion transcripts." (PMID 41019082, 2025).